LINC01126 (long independently transcribed non-coding RNA 1126)
Gene: Long non-coding RNA gene on chromosome 2 (43,219,805 to 43,233,464, forward strand). Ensembl gene ENSG00000279873.
Diseases named in the same sentence as LINC01126 in open-access papers:
LINC01126 is named in the same sentence as 2 diseases in open-access papers, as found by Europe PMC text mining. Sharing a sentence is not in itself a finding about the gene and the disease. The quoted sentences say what the papers report.
periodontitis (1 paper, 2021). An acute or chronic inflammatory process that affects the tissues that surround and support the teeth. "Taken together, combined with the microarray results and the aberrant expression in periodontal tissues, we hypothesized that LINC01126 was highly correlated with periodontitis pathogenesis and we selected it to further verify its functions in periodontitis pathogenesis." (PMID 33231338, 2021).
tumor (2 papers, 2023 to 2024). "We found that CDKN2B‐AS1, YEATS2‐AS1, MIR924HG, SLC16A1‐AS1, LRRC8C‐DT, and LINC01126 expression levels were significantly correlated with clinical stage and tumor grade in EC." (PMID 36525280, 2023). "We found that LINC01126 was preferentially expressed in metastatic CRPC tumours." (PMID 38214432, 2024). "SLC16A1‐AS1, LRRC8C‐DT, and LINC01126 expression was higher in normal tissues than in tumor tissues, and SLC16A1‐AS1, LRRC8C‐DT, and LINC01126 expression increased with an increase in clinical stage and tumor grade." (PMID 36525280, 2023).